HMGB1 (high mobility group box 1)
Diseases named in the same sentence as HMGB1 in open-access papers (continued):
Sharing a sentence is not in itself a finding about the gene and the disease.
infection (continued). "The aim of this study was to evaluate the utility of five markers of infection: C-reactive protein (CRP), procalcitonin (PCT), soluble triggering receptor expressed on myeloid cells-1 (sTREM-1), CD163 and high mobility group box-1 (HMGB1), as markers of SBI in severely ill Malawian children." (PMID 19675669, 2009). "During HAdV-C5-infection, HMGB1 may have both positive and negative roles." (PMID 39611842, 2025). "In addition, contact with Pseudomonas aeruginosa has been reported to stimulate IL-33 but not HMGB1 expression, and this finding might correlate this infection with an increased Th2 reaction." (PMID 36675299, 2023). "Therefore, to investigate whether autophagy plays a part in reducing the HSV-HMGB1 cytotoxicity in hypoxic conditioned HT29 cells, we examined the level of LC3-II expression in HCT116, SW480, and HT29 after infection with HSV- HMGB1 and HSV-ble during hypoxia and normoxia." (PMID 35477503, 2022). "Thus, HMGB-1 might increase in NEC, in which both infection and hypoxia play an important role." (PMID 36582510, 2022). "Similarly, analyses of biopsies taken from a patient with erysipelas at the center of infection, distal (5 cm outside the lesion) and healthy region (other non-infected leg) demonstrated that both HMGB1 and bacterial load increased with more involved inflamed tissue." (PMID 24524027, 2014). "HMGB1, which normally acts intracellularly as a nuclear non-histone DNA-binding protein, has been proposed to act as a cytokine that mediates a response to infection and inflammation when it is released actively from intact cells or passively from necrotic cells." (PMID 23071790, 2012). "Therefore, we investigated whether various activation signals, such as proinflammatory stimuli (TNF-α or IL-2 or IL-15), or signals that mimic infection (LPS, SEB or PMA), influence the cell surface expression and active secretion of HMGB1 by human cord blood cells." (PMID 21915243, 2011). "However, recent studies have revealed that some inflammatory markers such as the high-mobility group box-1 protein (HMGB1), the lipopolysaccharide-binding protein (LBP) and the Interleukin-6 (IL-6) may be detectable already in the early state of infection and bacteraemia." (PMID 20158885, 2010). "Infection in THE cells did not alter mRNA expression for HMGB1 over 48 hpi, indicating that release of HMGB1 from infected corneal epithelial cells was due to either cell death or to post-translational modifications rather than to increased gene expression." (PMID 40367285, 2025). "However, the deltas of the DAMP, HMGB1, in the group that developed SIRS were much higher than those of the group that did not develop SIRS and were above zero, which allows us to infer that it is associated with SIRS in patients with ALL without apparent infection." (PMID 40868835, 2025). "After infection with recombinant KSHV and KSHV BAC16, we selected KSHV-infected cells and found that HMGB1 expression in the cellular fraction was not significantly altered by KSHV infection." (PMID 37520371, 2023). "In regard to GLY mediated protection, in the current study, GLY was unable to reduce the levels of RAGE and HMGB1 in the absence of TLR9, but significantly reduced TLR4 levels in TLR9KO corneas after infection." (PMID 36422579, 2022). "This site differs from the LPS binding site, making it possible to selectively inhibit HMGB1/TLR4 activation without compromising LPS/TLR4 binding and its protective effects after infection." (PMID 34684184, 2021). "The authors found multiple alarmins (HMGB1, IL-33, S100A8, and S100A9) in the joint capsule of the FS patient group in amounts consistent with an infection, while in the control group they found no significant increase of infection related markers." (PMID 34046418, 2021).
infection (continued). "Whereas vehicle-inoculated mice did not express HMGB1 in the ASM, its expression increased incrementally over the course of infection in the ASM bundles of IRF7-/- but not WT mice, similar to the pattern of ASM growth." (PMID 32658914, 2020). "We used a fixed amount of anti-TNF-α and anti-HMGB-1 agent for our treatment, which fails to compromise an elevated level of TNF-α and HMGB-1 at a later stage of infection." (PMID 27556404, 2016). "Although HMGB1 can be passively secreted by activated dendritic cells and macrophages, infection of macrophages with Y. pestis expressing YopJC172A, which would activate macrophages through LPS-TLR4 signaling, did not result in HMGB1 release." (PMID 22563435, 2012). "When we considered the HMGB1 levels in children that had SARS-CoV2 infection 1 month prior, without any long-term complication, we found higher levels of HMGB1 than healthy controls, even in the absence of clear symptoms during the acute phase of infection." (PMID 35558368, 2022). "High mobility group box 1 (HMGB1), which is described as a highly conserved non-histone DNA-binding protein, was discovered to be a crucial cytokine that mediates the response to infection, injury, and inflammation." (PMID 33133061, 2020). "Interestingly, ΔYopM infection in BMDMs failed to upregulate NLRP3 and HMGB1 secretion, but significantly induced caspase-1 activation and IL-1β secretion." (PMID 27929533, 2016). "Thus, HMGB1 is an important factor for the maturation of both uninfected and HIV-1-infected iDCs during NK-DC cross talk, and it involves RAGE, whose expression on iDC is not altered following their productive infection." (PMID 18974890, 2008).
inflammation (60 papers, 2008 to 2026). Aberrant reaction of the microcirculation characterized by movement of fluid and leukocytes from the blood into extravascular tissues. "Intraoperative RBC transfusion enhances susceptibility to lung inflammation through the release of HMGB1 and induces necroptosis of lung endothelial cells." (PMID 36944948, 2023). "In this study, pregnant women with active medical conditions and immune system disease were excluded because recent study has highlighted a close association between HMGB1, chronic inflammation, and autoimmune diseases." (PMID 35477735, 2022). "In vivo, HMGB1 causes acute lung inflammation, epithelial-cell barrier leakage and even mortality." (PMID 23737912, 2013). "Chronic obesity-related inflammation activates the HMGB1/TLR4/NF-κB signaling cascade, while concurrent downregulation of SIRT1 further amplifies pro-inflammatory signaling." (PMID 41505418, 2026). "We sought to determine if epithelial cell-derived HMGB1 contributes to the delayed-onset corneal stromal inflammation characteristic of adenoviral keratoconjunctivitis." (PMID 40367285, 2025). "Because of the versatile role of HMGB1, we decided to explore the role of HMGB1-RAGE activation in renal inflammation." (PMID 38201260, 2023). "Studies have shown that HMGB1 exists in the early stages of pulmonary inflammation and late fibrosis, and glycyrrhizic acid inhibits the expression of HMGB1, which can slow down the progression of pulmonary inflammation and fibrosis." (PMID 35886594, 2022). "In this study, the mechanical stretch (MS) on VSMCs, which mimics increased pressure in the vasculatures, showed an increase in the release of HMGB1, a major DAMP implicated in vascular inflammation." (PMID 35294955, 2022). "Among several candidate proteins, heat shock protein 90 regulates the nucleocytoplasmic translocation of HMGB1 and mitochondrial heat shock protein 75 (or glucose-regulated protein 75) is involved in HMGB1-induced asthmatic airway inflammation." (PMID 36585612, 2022). "Recently, it has been shown that HMGB1 prolongs and enhances the febrile response to a low LPS dose (50 μg/kg) after turpentine pre treatment, suggesting a role for HMGB1 as a trigger of brain inflammation and as an endogenous pyrogen." (PMID 34208101, 2021). "Lung inflammation, HMGB1 protein levels, and HMGB1 expression in inflammatory cells were increased in Hmox1−/− mice relative to wild type mice." (PMID 34073678, 2021). "Studies have shown that AMPK activation suppressed de novo lipogenesis, and the HMGB1/TLR4/NF-κB pathway was involved in liver inflammation." (PMID 33959665, 2021). "In the state of vascular inflammation, the complex of HMGB1 and hemoglobin binds to CD163, activating monocytes and promoting the expression of inflammatory factors." (PMID 33997033, 2021). "Both in vivo and in vitro studies have demonstrated that HMGB1 is critical for the development of vascular inflammation." (PMID 31011475, 2019). "In a model of erythrocyte transfusion and LPS-induced lung inflammation, necroptosis of lung endothelial cells is induced via high mobility group box 1 (HMGB1) protein." (PMID 27116944, 2016). "Anti-HMGB1 antibody reduced MCT-induced lung inflammation as shown by a decrease in infiltrating leukocytes in BALF." (PMID 25032709, 2014). "Intra-tracheal administration of HMGB1 in mice induces acute lung inflammation, with accumulation of neutrophils, edema, and production of pro-inflammatory cytokines." (PMID 23351605, 2013). "In the present study, we demonstrated further that hyperoxia increased high tidal volume ventilation-induced HMGB1 mRNA expression and HMGB1 production, a late mediator of lung inflammation, in a short duration of mechanical ventilation." (PMID 21726460, 2011).
inflammation (continued). "Pathogen-associated molecular patterns (PAMPs) such as LPS, as well as Damage-associated molecular patterns (DAMPs) including High mobility group box 1 (HMGB1), can all activate NF-κB by acting on Toll-like receptors (TLRs), especially Toll-like receptor 4 (TLR4), leading to liver inflammation." (PMID 41154556, 2025). "Of note, anti-HMGB1 therapy was effective in significantly reducing disease severity even when administered days after onset of severe inflammation, and anti-HMGB1 antibodies and HMGB1-targeted sorption beads have a protective effect in experimental intestinal inflammation." (PMID 35095387, 2021). "As macrophages play an important role in orchestrating pulmonary innate immunity, we then asked whether myeloid-specific PTEN might affect HMGB1-mediated lung inflammation." (PMID 25759027, 2015). "To further elucidate the mechanism by which PTEN/Foxo1 signaling may regulate HMGB1-induced lung inflammation, we isolated alveolar macrophages in BALF from rHMGB1-instilled lungs." (PMID 25759027, 2015). "By using a mouse model of HS/R, we tested the hypothesis that HS/R induces gut injury and further leads to increase in circulating levels of HMGB1; the latter effect results in lung inflammation and injury." (PMID 25309129, 2014). "However, there are already available compounds that have been approved for HMGB1-independent purposes, which might be considered for clinical use to inhibit excessive HMGB1 proinflammatory activities in exaggerated pulmonary inflammation." (PMID 32380958, 2020). "Thus, endothelial cells are damaged by cytotoxic release of extracellular HMGB-1, which may then act as an inflammatory mediator, thereby resulting in a pathological cycle that leads to persistent subacute chronic vascular inflammation in KD." (PMID 28255175, 2017). "The authors found that the neutralizing antibody-mediated abrogation of HMGB1 attenuated silica-induced lung inflammation, fibrosis, and EMT, whereas the application of recombinant HMGB1 exerted the opposite effect." (PMID 38515835, 2024). "It directly blocks the binding of HMGB1 to RAGE, thus preventing retinal vascular inflammation." (PMID 32722545, 2020). "These histological findings are consistent with our previous publication that HMGB1 mediates bladder pain without overt bladder inflammation." (PMID 28545586, 2017). "In contrast to Wt mice, Faslps mice exhibited no, or only very mild, ocular inflammation and only very low levels of HMGB1 in the ocular fluid." (PMID 26394985, 2015). "Previous evidences have documented that HMGB1, RAGE and IL-17 are involved in liver inflammation." (PMID 26391982, 2015). "In addition, we examined the release of the high-mobility group box 1 (HMGB1) protein, a late phase mediator of acute lung inflammation, from Legionella-infected alveolar epithelial cells." (PMID 18447956, 2008). "Previous studies have demonstrated that HMGB1 can directly activate macrophages and activated alveolar macrophages could produce chemokines to recruit PMN to the lungs and exaggerate lung inflammation and consequently ALI, but the exact mechanism(s) by which HMGB1 induces ALI remains unknown." (PMID 25309129, 2014).
cardiovascular diseases (56 papers, 2012 to 2026). "There is a well-established literature related to the sartan compounds such as telmisartan, irbesartan, and candesartan suggesting their role in treating various inflammatory conditions associated with cardiovascular diseases via the HMGB1/RAGE axis." (PMID 36364135, 2022). "In cardiovascular disease, cells are stimulated by pathogenic factors to release HMGB1, an inflammatory mediator." (PMID 36544080, 2022). "Risk factors for cardiovascular disease, carotid ultrasound, HMGB1 and sRAGE levels in GPA patients and controls." (PMID 24776932, 2014). "By elucidating the role of this alarmin in adipocyte function, we identify HMGB1 as a promising therapeutic target for tackling both metabolic disorders and cardiovascular disease." (PMID 40362460, 2025). "High-mobility group box 1 (Hmgb1) serves as an inflammation driver and mediator of cardiovascular disease." (PMID 35743792, 2022). "In the development and progression of cardiovascular diseases, HMGB1 is one of the best characterized DAMPs among various injury-induced mediators." (PMID 35294955, 2022). "Among the various injury-induced mediators, HMGB1 is one of the best characterized DAMPs in the development and progression of cardiovascular diseases." (PMID 34803747, 2021). "In the initial stage of cerebrovascular and cardiovascular diseases, HMGB1 is released from the cell to participate in the cascade amplification reaction of inflammation, causing vasospasm and apoptosis." (PMID 33503060, 2021). "High mobility group box 1 (HMGB1), a pivotal inflammatory mediator, plays a potential role as a prognostic biomarker in cardiovascular disease." (PMID 32286371, 2020). "Recently, high mobility group box-1 (HMGB1) has been proposed as a potent pro-inflammatory cytokine that participates in the development of cardiovascular diseases." (PMID 31011475, 2019). "Emerging evidence indicates that HMGB1 also contributes to the pathogenesis of cardiovascular diseases." (PMID 31336567, 2019). "Moreover, HMGB1 remains persistently elevated in various cardiovascular diseases, including AF, and plays a particularly prominent role in atrial structural remodeling." (PMID 40989585, 2025). "Blocking HMGB1’s inflammatory signaling pathways holds promise as a novel therapeutic strategy for cardiovascular diseases, while modulating HMGA2 expression has the potential to delay disease progression by improving myocardial remodeling and repair processes." (PMID 39507236, 2024). "Different evidence shows a role of HMGB-1 in cardiovascular diseases development." (PMID 36244983, 2022). "HMGB1 is released from damaged cells and acts as a circulating damage-associated molecular pattern (DAMP) molecule that induces inflammatory, autoimmune, and cardiovascular diseases or neurological disorders." (PMID 34209885, 2021). "We also found that inhibition of HMGB1 could enhance the cardioprotective effect of taxifolin and might be a new therapeutic strategy for cardiovascular disease." (PMID 34567165, 2021). "A previous study showed that HMGB1 plays vital roles in the development of cardiovascular diseases." (PMID 33274007, 2020). "Therefore, an improved understanding of the release mechanism of HMGB-1 as well as the downstream effects in the light of IRI following MI or HTx will be critical for elucidating the various physiological roles of HMGB-1 in cardiovascular disease." (PMID 33363540, 2020). "Its ability to inhibit HMGB1 signaling and regulate key inflammatory and oxidative pathways suggests that GA could be useful in treating diseases characterized by excessive inflammation and oxidative stress, such as neurodegenerative diseases and cardiovascular disorders." (PMID 39598404, 2024). "The aim of this article is to comprehensively review the role of HMGB1, HIF-1α, and VEGF in DOX-induced Cardiovascular Disease and its molecular mechanisms." (PMID 35340325, 2022).
cardiovascular diseases (continued). "HMGB1, HIF-1α and VEGF has a pivotal regulator in DOX-induce cardiomyocyte damage in cardiovascular diseases which predominantly acts through different pathways." (PMID 35340325, 2022). "•HMGB1, HIF-1α, and VEGF in cardiovascular diseases will be predominantly acting through different pathways." (PMID 35340325, 2022). "One of the most selective HMGB1 inhibitor, TSN, has already been used in China as medication for patients with cardiovascular disorders." (PMID 26257917, 2015). "Relevant investigations of the role of the HMGB1/TLR4 axis in cardiovascular diseases are not uncommon." (PMID 38456997, 2024). "The data in this study were collect by search the keyword combinations of medical subject headings (MeSH) of “HMGB1”, “HIF-1 α”, “VEGF”, “DOX” and “Cardiovascular disease” and relevant reference lists were manually searched in PubMed, EMBASE and Scopus database." (PMID 35340325, 2022). "Several articles were revealed that molecular mechanisms of the DOX in cardiomyocyte damage and related to HMGB1, HIF-1α and VEGF and may potential treatment and prevention to cardiovascular disease in DOX intervention." (PMID 35340325, 2022). "Given its demonstrated safety in China as a medicine for patients with cardiovascular disorders, and its capacity to inhibit HMGB1 release after LPS stimulation, TSN-SS may be a promising therapeutic agent for inhibiting HMGB1 release in clinical settings." (PMID 34571869, 2021). "High mobility group box 1 (Hmgb1) is a DNA-binding nuclear nonhistone protein that plays an important role in the occurrence and development of cardiovascular diseases." (PMID 33110475, 2020). "Therefore, regulating HMG proteins, particularly HMGB1 and HMGA2, could have a significant impact on the treatment of cardiovascular diseases." (PMID 39507236, 2024). "Although compelling studies show that HMGB1 and TLR4 play pivotal roles in the pathogenesis of cardiovascular diseases and inflammatory response, but there was no literature about HMGB1/TLR4 signaling contributes to atherogenesis induced by CUMS." (PMID 30881312, 2019).